OR9G1 (olfactory receptor family 9 subfamily G member 1)
Description:
Odorant receptor.
Synonyms: OR9G5
Tractability: Antibody: its Gene Ontology location is reachable by antibodies, with high confidence; UniProt places it where antibodies can reach, with medium confidence; UniProt predicts a signal peptide or a membrane-spanning region.
Gene: Protein-coding gene on chromosome 11 (56,699,095 to 56,703,884, forward strand). Ensembl gene ENSG00000174914.
Subcellular location: Cell membrane
Pathways (Reactome):
Sensory Perception: Expression and translocation of olfactory receptors; Olfactory Signaling Pathway
Gene Ontology:
Molecular function: G protein-coupled receptor activity; olfactory receptor activity
Biological process: detection of chemical stimulus involved in sensory perception of smell; G protein-coupled receptor signaling pathway
Cellular component: plasma membrane; membrane
Genetic constraint (gnomAD): Loss-of-function variants: 21 observed, 13.67 expected, observed/expected ratio (o/e) 1.54, 90% interval 1.07 to 1.93. The synonymous counts are far from expectation, so gnomAD's model fits this gene poorly and the ratio says little. Missense variants: 476 observed, 317.82 expected, observed/expected ratio (o/e) 1.5, 90% interval 1.39 to 1.62. Synonymous variants: 179 observed, 124.03 expected, observed/expected ratio (o/e) 1.44, 90% interval 1.28 to 1.63.
Homologues: Orthologues: chimpanzee OR9G1 (97% identical), macaque OR9G1 (93% identical), dog OR9G1 (83% identical), rat Or9g20 (76% identical), mouse Or9g20 (76% identical). Paralogues in human: OR11H6 (43% identical), OR11H12 (43% identical), OR11H2 (42% identical), OR11H1 (42% identical), OR11G2 (42% identical), OR11A1 (41% identical), OR11H4 (41% identical), OR11H7 (41% identical), OR10X1 (38% identical), OR9A2 (35% identical), OR9A4 (35% identical), OR9A1P (32% identical), and 21 more.
Diseases named in the same sentence as OR9G1 in open-access papers:
OR9G1 is named in the same sentence as 3 diseases in open-access papers, as found by Europe PMC text mining. Sharing a sentence is not in itself a finding about the gene and the disease. The quoted sentences say what the papers report.
autism (1 paper, 2015). Persistent deficits in social interaction and communication and interaction as well as a markedly restricted repertoire of activity and interest as well as repetitive patterns of behavior. "These genes with identical genomic variants included KCNJ12, MLL3, OR9G1 and PCMTD1 with different mutations reported in other disease states and appeared to reflect artifacts in the present analysis of autism." (PMID 25574603, 2015).
OR9G1 also shares sentences with these, for which no sentence is quoted: cancer (1 paper); gastric cancer (1).